STSP1 (steroid sulfatase (microsomal) pseudogene 1)
Synonyms: STS-Y; STSP
Gene: Transcribed unprocessed pseudogene on chromosome Y (15,547,216 to 15,593,331, forward strand). Ensembl gene ENSG00000227166.
Diseases named in the same sentence as STSP1 in open-access papers:
STSP1 is named in the same sentence as 3 diseases in open-access papers, as found by Europe PMC text mining. Sharing a sentence is not in itself a finding about the gene and the disease.
STSP1 shares sentences with these, for which no sentence is quoted: cancer (1 paper); chronic myeloid leukemia (1); infection (1).